FBXW7 (F-box and WD repeat domain containing 7)
Diseases named in the same sentence as FBXW7 in open-access papers (continued):
Sharing a sentence is not in itself a finding about the gene and the disease.
glioma (continued). "In addition, FBXW7 was identified as a key downstream molecule of miR-155 in glioma cells." (PMID 40534867, 2025). "In addition, the circBRAF expression was downregulated in glioma, and it could suppress malignant behaviors of glioma via regulating the miR-1290/FBXW7 axis." (PMID 38075205, 2024). "Interrogation of the Chinese Glioma Genome Atlas (CGGA; data set: mRNAseq_693) (CGGA is included in GlioVis) showed that GBM patients with isocitrate dehydrogenase (IDH) mutations express lower FBXW7 mRNA levels as compared with GBM patients with wild-type (WT) IDH (***p=0.00086)." (PMID 37752997, 2023). "Moreover, FBXW7 was identified as a key downstream molecule of miR-155 in glioma cells." (PMID 35928868, 2022). "Similarly, while lncMALAT-1 overexpression can have tumor-suppressing effects in glioma cells through ceRNA of miR-155 and increased expression of FBXW7, lncRNA MALAT1 contributes to non-small cell lung cancer development via modulation of the miR-124/STAT3 axis." (PMID 35346215, 2022). "In addition to the well-known and highly recurrent events, GTS defines and ranks many previously unrecognized CNAs, uncovers frequent codeletion of two related CKI genes, CDKN2C and CDKN2A, in human cancers, and implicates APAF1 and FBXW7 in glioma pathogenesis." (PMID 18394558, 2008). "Finally, FBXW7 knockdown in U87 cells leads to defects in mitosis that may promote aneuploidy in progressing glioma." (PMID 17326833, 2007). "F-box and WD repeat domain containing 7 (FBXW7), another SCF E3 ubiquitin ligase substrate recognition element, is inversely related to the expression of IDH1 in gliomas." (PMID 35392171, 2022). "Since, FBXW7 mRNA is a direct target of miR-155 in glioma, downregulating miR-155 by MALATI resulted in an enhanced expression of FBXW7, thereby suppressing the glioma cell proliferation." (PMID 30791487, 2019). "In this study, we investigated the expression of FBXW7 (also known as hCDC4, hAGO, SEL10) in glioma." (PMID 17326833, 2007). "Besides, FBXW7, among other ligases, modulates the proteasomal degradation of MYC, an oncological transcriptional factor generally overexpressed in gliomas." (PMID 33665742, 2021). "We analyzed the data from the CGGA database and revealed the negative correlation of RANBP10 and FBXW7 in glioma." (PMID 34671019, 2021). "Another study reported that MALAT1 upregulated FBXW7 expression by modulation of the MALAT1-miR-155 pathway, which might serve as a novel prognostic biomarker and therapeutic target for glioma." (PMID 28977880, 2017). "The miR-10b regulated expression of FBXW7, and FBXW7 effects on the cell cycle machinery in glioma cell are in agreement with the reports showing that FBXW7 is frequently down-regulated in GBM, and its overexpression blocks proliferation of glioma cells." (PMID 25738367, 2015). "Notably, FBXW7 mediated the carcinogenesis of U87 and SHG139 glioma cells induced by miR-155." (PMID 40534867, 2025). "Notably, FBXW7 mediated miR-155-triggered oncogenesis in U87 and SHG139 glioma cells." (PMID 35928868, 2022). "Importantly, we found that knock-down of FBXW7 increases the levels of several cell cycle proteins, such as E2F1, LSH, KI67, Cyclin A2 and Cyclin E2, both in basic conditions, as well as in miR-10b – depleted glioma cells." (PMID 25738367, 2015). "Actb, FBXW7 and HPRT1 were differentially expressed between glioma samples and non-tumour controls and were therefore excluded as housekeeping genes." (PMID 41034696, 2025).
hepatocellular carcinoma (45 papers, 2014 to 2025). A malignant tumor that arises from hepatocytes. "Notable examples include circHGF, which encodes C-HGF to activate c-MET signaling and promote glioblastoma growth, and circZKSCAN1, which suppresses hepatocellular carcinoma through its interaction with FBXW7 and mTOR, thereby inhibiting the PI3K/AKT pathway." (PMID 40730815, 2025). "The same is true for miR-92a regulation of FBXW7 in hepatocellular carcinoma (HCC); where overexpression of miR-25-3p and miR155-3p have also been shown to suppress FBXW7 mRNA expression, promoting the migration and invasion of tumor cells." (PMID 35346215, 2022). "Wnt/β‐catenin signalling was shown to have an inhibitory effect on microRNA‐770 expression and further suppressed FBXW7 expression, resulting in the enhancement of hepatocellular carcinoma." (PMID 32394588, 2020). "In addition to GBM, miR-25 also inhibits FBXW7, increasing the resistance of hepatocellular carcinoma to sorafenib." (PMID 36998461, 2023). "FBXW7 expression is reduced in hepatocellular carcinoma (HCC) tissues." (PMID 34659544, 2021). "Additionally, miR-92a acts as an onco-miRNA in promoting tumor growth of hepatocellular carcinoma (HCC) via inhibition of F-box and WD repeat domain-containing 7 (FBXW7)." (PMID 30804710, 2019). "In hepatocellular carcinoma (HCC), overexpression of miR-155-3p induces FBXW7 to be downregulated at both mRNA and protein levels." (PMID 36998461, 2023). "In addition to β-TrCP-dependent ubiquitination, human YAP has also been shown to be ubiquitinated by the E3 ligase F-box and WD repeat domain-containing 7 (Fbxw7) in hepatocellular carcinoma cells, in which Fbxw7 levels correlate inversely with YAP protein levels." (PMID 37031213, 2023). "In hepatocellular carcinoma cells, YAP has been shown to undergo ubiquitination mediated by the E3 ligase F-box and WD repeat domain-containing 7 (Fbxw7), with an inverse relationship observed between Fbxw7 expression and YAP protein levels." (PMID 40478800, 2025). "The study shows that RPAP2, acting as an oncoprotein, promotes hepatocellular carcinoma (HCC) progression, with its stability being negatively regulated by FBXW7, yet positively by HSP90 and USP7." (PMID 39932049, 2025). "E3 ubiquitin ligases, such as the F‐box and WD40 repeat domain containing‐7 (Fbxw7) and β‐TrCP destabilize YAP1 by targeting it for ubiquitination and proteasomal degradation in hepatocellular carcinoma (HCC) and pancreatic cancer." (PMID 39968498, 2025). "DDX39B inhibits FBXW7-mediated ubiquitination and degradation of SREBP1, leading to increased lipid accumulation and promoting progression in hepatocellular carcinoma." (PMID 39944823, 2025). "For example, TRIP13 plays an oncogenic role in glioblastoma via the FBXW7/c-MYC pathway and induces hepatocellular carcinoma (HCC) cell migration, invasion, and metastasis through AKT/mTOR signaling via and interaction with ACTN4." (PMID 38012658, 2023). "For instance, Fbxw7 regulates YAP protein stability by targeting YAP for ubiquitination and proteasomal degradation in hepatocellular carcinoma; SHARPIN and RNF187 promote YAP degradation via inducing YAP K48-dependent poly-ubiquitination." (PMID 37349820, 2023). "For instance, we found that lncRNA CASC2 suppresses epithelial-mesenchymal transition of hepatocellular carcinoma cells through the CASC2/miR-367/ F-box and WD repeat domain containing 7 (FBXW7) axis." (PMID 33596983, 2021). "Likewise, PRMT5-methylation of SREBP1, a transcription factor required for de novo lipogenesis, prevents its phosphorylation by GSK3β and subsequent ubiquitination by FBXW7, thereby increasing lipogenesis and tumor growth of hepatocellular carcinoma (HCC)." (PMID 32743345, 2020). "FBXW7 expression is also reduced in hepatocellular carcinoma (HCC) tissues." (PMID 30086763, 2018).
hepatocellular carcinoma (continued). "In addition, circFBXW7 is an antioncogenic product encoded by the Fbxw7 protein that acts as a tumor suppressor, and circFBXW7 is down-regulated as a result of mutation in hepatocellular carcinoma (HCC) and esophageal cancer, clarifying the role of Fbxw7 in the mechanism of HCC development." (PMID 39727990, 2024). "It was suggested that F-box and WD repeat domain-containing 7 (Fbxw7), a well-known F-box protein in the SCF (SKP1-CUL1-F-box protein) E3 ligase complex, can directly bind to YAP and decreases the accumulation of YAP in hepatocellular carcinoma cells." (PMID 30486435, 2018). "In addition, the ubiquitination of YAP by Fbxw7 and its subsequent proteasomal degradation enhance apoptosis in hepatocellular carcinoma cells, while restoring YAP expression partially abrogates Fbxw7-induced cell apoptosis and growth arrest in vitro and in vivo." (PMID 35606801, 2022). "A previous study showed that the expression of FBXW7 in hepatocellular carcinoma (HCC) clinical samples was lower than that in the adjacent nontumor tissues and was negatively correlated with the invasion and migration of HCC cells." (PMID 36159747, 2022). "In terms of targeting FBXW7 itself, the downregulation of prolyl isomerase Pin1 contributes to upregulation of FBXW7 and ensuing destruction of MCL-1, which potentiates the toxicity of sorafenib to prevent cell proliferation and induce apoptosis in hepatocellular carcinoma (HCC)." (PMID 35515121, 2022).
colon carcinoma (40 papers, 2009 to 2025). "In colon cancer cells, FBXW7 deficiency results in accumulation of mTOR, thus in turn favoring EMT-related stem-like properties." (PMID 35515121, 2022). "It is reasonable to have a tumor suppressor E3 ligase FBXW7, which is frequently mutated in colon cancer, to degrade a potential oncogenic protein CHD6." (PMID 36473865, 2022). "We focused on mTOR, since our previous study showed that mTOR inhibition by rapamycin suppresses EMT, invasion and stemness driven by loss of FBXW7 in colon cancer cells." (PMID 24344117, 2013). "Moreover, FBXW7 deficiency stimulates the production of colon cancer stem-like cells in tumor-sphere culture." (PMID 41373479, 2025). "Arterial CTCs and venous CTCs of patients with colon cancer can detect more mutated genes than tissue, and arterial CTCs can detect the mutated genes targeted with clinically available drugs (Fbxw7), while tissues can also detect the mutated genes targeted with clinically available drugs (KRAS)." (PMID 34134721, 2021). "In vitro study of FBXW7-mediated CDX2 ubiquitination using coimmunoprecipitation and phosphodegron mutations in colon cancer and HEK293T cells." (PMID 41373479, 2025). "FBXW7 has been identified as a direct target of miR-27a in colon cancer cells, where upregulation of miR-27a promotes cell proliferation, likely due to the inhibition of FBXW7 expression and subsequent elevation of cyclin E levels." (PMID 40534867, 2025). "FBXW7 and GSK3β overexpression reduces CDX2 levels and function, causing growth arrest in colon cancer cells; disruption of both CDX2 phosphodegrons prevents FBXW7-mediated degradation." (PMID 41373479, 2025). "FBXW7 (F-Box and WD repeat domain containing 7, E3 ubiquitin-protein ligase of C-Jun) has been reported to be carcinogenic in colon cancer." (PMID 35341150, 2022). "Overexpression of KDM5c in human colon cancer cells leads to weakened FBXW7 transcription and increases c-Jun protein, resulting in the proliferation of colon cancer cells." (PMID 35248043, 2022). "For example, KDM5C promotes the proliferation of colon cancer cells through the FBXW7-c-Jun regulatory axis." (PMID 35248043, 2022). "Here, we report that overexpression of KDM5c in human colon cancer cells results in attenuated FBXW7 transcription and accumulated c-Jun protein, leading to increased proliferation of colon cancer cells." (PMID 33042830, 2020). "Specifically, KDM5c protein level can alter colon cancer cell growth by deregulating transcription of the cancer cell repressor gene FBXW7, thereby, modulating c-Jun degradation via the ubiquitin-proteasome pathway." (PMID 33042830, 2020). "Our results showed that KDM5c accelerated proliferation of colon cancer cells by down-regulating FBXW7 transcription, thereby, reducing c-Jun degradation via the ubiquitin-proteasome pathway." (PMID 33042830, 2020). "To further study the role of E3-Ubl FBXW7 in the regulation of endogenous CCDC6 protein during the cell cycle we employed the HCT116 FBXW7−/− colon cancer cells." (PMID 25885523, 2015). "In vitro study using FBXW7 knockout colon cancer cell lines." (PMID 41373479, 2025). "Moreover, our results confirmed that DGG200064 selectively inhibited c-Jun ubiquitination by FBXW7 in colon cancer cell lines: DGG200064 binds to FBXW7 (aa 626–689) and inhibits its interaction with c-Jun." (PMID 35631329, 2022). "In colon cancer cells, the lysine demethylase KDM5c could attenuate FBXW7-mediated degradation of c-Jun by epigenetically modifying FBXW7 and decreasing FBXW7 transcription, further promoting cell proliferation." (PMID 35515121, 2022). "FBXW7 is an E3 ubiquitin ligase of c-Jun, and exhibits carcinostasis in colon cancer." (PMID 33042830, 2020). "However, colon cancer cells co-transfected with KDM5c, FBXW7, and c-Jun as KDM5c-OE/FBXW7-OE/c-Jun-OE cells, exhibited significantly increased cell growth and increased colony formation, with more G2/M phase cells and fewer G1 phase cells." (PMID 33042830, 2020).
colon carcinoma (continued). "Additionally, miR-182 and miR-503 are sequentially upregulated in colon cancer cells and synergistically target FBXW7 for genetic repression, further highlighting the role of microRNAs in modulating FBXW7 expression and its downstream effects on cell cycle regulation and cancer progression." (PMID 40534867, 2025). "Through two phosphodegron motifs found within CDX2, FBXW7 promotes CDX2 ubiquitination and degradation in a GSK3β-dependent manner, resulting in decreased CDX2 expression and activity in colon cancer cells." (PMID 41373479, 2025). "A positive feedback loop consisting of NICD/Hes5/FBXW7 was identified in colon cancer cells, where the negative regulation of FBXW7 by Hes5, particularly its repressive effect on the transcription of FBXW7, is extremely significant." (PMID 36998461, 2023).
lung carcinoma (40 papers, 2015 to 2025). "More mutated genes can be detected in arterial CTCs of patients with lung cancer compared with tissues and venous CTCs, and the mutated genes targeted with clinically available drugs (Fbxw7) can only be detected in arterial CTCs." (PMID 34134721, 2021). "In this study, we investigated the functions of FBXW7 and its potential associated regulators in lung cancer tumorigenesis." (PMID 33676554, 2021). "Additionally, terminal differentiation-induced lncRNA (TINCR) was found to inhibit lung cancer cell proliferation and invasion by sequestering miR-544a from its target FBXW7, which caused an increased upregulation of FBXW7." (PMID 30791487, 2019). "The reduction in FBXW7 mRNA level is associated with poor overall survival in lung cancer patients." (PMID 29633504, 2018). "To determine whether reduced FBXW7 expression is associated with clinical outcome of lung cancer patients, we further evaluated the prognostic value of FBXW7 in a large public clinical microarray database." (PMID 29633504, 2018). "That is, lncRNA TINCR exerts anti-proliferation and invasion ability in lung cancer cells by regulating the miR-544a/FBXW7 axis." (PMID 40534867, 2025). "Building upon this knowledge, we screened for dysregulated circRNAs in Osimertinib-resistant lung cancer groups and investigated the suppressed circ-FBXW7's role in controlling the functional EGFR pathway." (PMID 37393311, 2023). "The lncRNA TINCR, as a ceRNA, cleaves miR-544a from its target gene FBXW7 to regulate the proliferation and invasion of lung cancer cells." (PMID 36833217, 2023). "Altogether, lncRNA TINCR performed anti-proliferative and invasive abilities in lung cancer cells through modulating miR-544a/FBXW7 axis." (PMID 35928868, 2022). "Perifosine induces the degradation of key proteins in the mTOR axis through a GSK3/FBXW7-dependent mechanism in human lung cancer cells." (PMID 32577098, 2020). "Together, these clinical data indicate that the expression levels of FBXW7 are reduced during lung cancer development and that reduced FBXW7 expression correlates with poor clinical outcome." (PMID 29633504, 2018). "FBXW7 was confirmed to be a downstream target of miR-544a in lung cancer cells." (PMID 40534867, 2025). "MiR-27a increased lung cancer cell growth by inhibiting FBXW7, demonstrating that FBXW7 could act as a tumor suppressor." (PMID 37635248, 2023). "FBXW7 has been demonstrated to play a key role in lung cancers regulated by miRNAs." (PMID 34869091, 2021). "Hence, these studies indicate the important function of FBXW7 in inhibiting lung cancer development and progression." (PMID 30791487, 2019). "According to the TCGA data analysis, mutation frequency of FBXW7 was found to be 2.2% in 507 lung adenocarcinomas cases studied and 4.7% in lung squamous cell cancer cases studied which remarkably resulted in downregulation of FBXW7 leading to a poorer prognosis of lung cancer patients." (PMID 30791487, 2019). "Moreover, FBXW7 was validated as a downstream target of miR-544a in lung cancer cells." (PMID 35928868, 2022). "However, the m6A modifications governing FBXW7 stability and/or function in cancers and how FBXW7 expression may be modulated by m6A modification in lung cancer remain largely unknown." (PMID 33676554, 2021). "To further determine the role of FBXW7 in the polarization of M2-like TAMs, we stimulated macrophages with LLC supernatant to mimic the lung cancer condition and detected the expression of FBXW7 in M2 macrophages." (PMID 33260160, 2020).
lung carcinoma (continued). "Moreover, LSD1 directly binds to FBXW7 to destabilize FBXW7, leading to abrogating FBXW7’s functions in growth suppression, nonhomologous end-joining repair (NHEJ), and radioprotection in lung cancer cells." (PMID 37973845, 2023). "Substantial evidence has confirmed that FBXW7 plays a negative role in the pathogenesis of lung cancers." (PMID 33676554, 2021). "Furthermore, treatment with decitabine, in vitro lung cancer cells, and in vivo lung cancer xenograft mouse models reverted the FBXW7 promoter to a non-methylated state, resulting in increased expression of FBXW7." (PMID 39748950, 2024). "However, levels of MALAT1 are elevated in NSCLC, which suggests MALAT1 and/or miR-155 do not play a significant role in FBXW7 regulation and implies that the MALAT1/miR-155/FBXW7 axis may have a tumor suppressor role in lung cancer." (PMID 30086763, 2018).